CCL17 (C-C motif chemokine ligand 17)
Diseases named in the same sentence as CCL17 in open-access papers (continued):
Sharing a sentence is not in itself a finding about the gene and the disease.
melanoma (continued). "Both RNAseq and NanoString analyses showed that melanoma tumors grown in Siah2−/− mice exhibit reduced expression of Ccl17 and Ccl22, chemokines expressed by tolerogenic DCs49,50, along with increased expression of Cxcl9, a chemokine functioning in T cell recruitment to tumor sites." (PMID 31911617, 2020). "We suggest that the up-regulated levels of CCL17 in the brain could chemo-attract CCR4-expressing melanoma cells towards this organ." (PMID 28415693, 2017). "In-vitro, CCL17 induced migration and transendothelial migration of melanoma cells." (PMID 28415693, 2017). "In line with our hypothesis, microglial cells co-cultured with melanoma cells secreted higher levels of both CCL17 and CCL22 than microglial cells grown alone." (PMID 28415693, 2017). "We next asked whether astrocyte-induced melanoma cell migration could be mediated by the CCR4 ligands CCL17 and/or CCL22." (PMID 28415693, 2017). "Neutralizing CCL17 with specific Ab added to conditioned medium of the astrocytes, significantly inhibited the migration and transendothelial migration of brain metastasizing melanoma cells." (PMID 28415693, 2017). "Notably, the expression of the CCR4 ligands, Ccl22 and Ccl17 is upregulated at the earliest stages of brain metastasis, and precedes the infiltration of melanoma cells to the brain." (PMID 28415693, 2017). "However, levels of CCL17 may represent a marker of interest to study in HNC, as increased serum levels have been shown to be associated with longer survival in melanoma patients with metastasis." (PMID 35682983, 2022). "The major chemokine/chemokine receptor interactions occurring in melanoma development and progression include the CXCR4/CXCR7/CXCL12, CXCR3/CXCL9,10,11, CXCR1,2/CXCL8, CCR2/CCL2, CCR4/CCL17,22, CCR5/CCL5, CCR7/CCL21 and CCR10/CCL27 axes." (PMID 37170733, 2023). "CC chemokine ligand CCL17, a CCR4 ligand, was discovered to be released by BECs, astrocytes, and microglia, with their interaction driving melanoma cell migration toward the brain." (PMID 37190188, 2023). "Higher expression of chemokines (e.g., CCL17 and CCL22) that attract anti-tumor immune cells was found in FGFR mutant melanoma." (PMID 36426352, 2022). "Regarding chemokines, CCL1, CCL17, CCL22 and CCL23, were significantly increased in FGFR Mut melanoma (all P < 0.05)." (PMID 36426352, 2022). "Studies using a melanoma brain metastasis immunocompetent mouse model revealed an upregulation in proinflammatory cytokines CXCL10, CCL17, CCL2, IL6, and IL-1β." (PMID 33466236, 2021). "Further analyses show that SK1 knockdown in melanoma tumors potently reduced the production of various immunosuppressive cytokines such as TGFβ, IL10, CCL17, and CCL22, which is in line with the strong decrease of Treg tumor infiltration." (PMID 31974367, 2020). "Certain chemokines, including IL-8, CCL4, CCL17, and CXCL10, in the cerebrospinal fluid may predict brain metastases in melanoma patients." (PMID 37525217, 2023). "CX3CL1 and CXCL13 were shown to play an important role in the brain extravasation of breast cancer, while the following cytokines/chemokines were involved in the extravasation of melanoma cells (9IL-23, CXCL10, CXCR3, CXCL10 receptor, CCR4, CCL17, and CCR4) and lung cancer cells (TNF-α and CX3CR1)." (PMID 37190188, 2023). "In another study, we showed that brain microenvironmental cells including astrocytes expressed and released CCL17 and CCL22 two chemokine ligands of the chemokine receptor CCR4, which is expressed by a subpopulation of melanoma cells with brain‐metastasizing capacity." (PMID 32761606, 2021). "In some cancers, an increased expression of CCR4 ligands (CCL17 and CCL22) in a tumor may play an anti-tumor role in colon carcinoma, lung cancer, ovarian cancer and melanoma, resulting in an increase in CD4+ T cells and CD8+ T cells." (PMID 33182504, 2020).
melanoma (continued). "Because CCL17 and CCL22 from TAMs attracts Tregs to the tumor site in melanoma, repolarization of TAMs by immunomodulatory reagents such as IFN-β and imiquimod are useful for suppressing tumor growth in melanoma." (PMID 29410946, 2018). "In addition, TAMs are prominent in the tumor stroma in melanoma, and POSTN stimulates CD163+ macrophages to produce several specific cytokines including Treg-related chemokines [chemokine ligand 17 (CCL17), CCL22]." (PMID 29410946, 2018). "Other reports have suggested that a series of chemokines (CCL17, CXCL10, CCL4, and IL-8) in cerebrospinal fluid may be useful for predicting brain metastasis in melanoma patients." (PMID 29410946, 2018). "Further, analysis of clusters identified within the melanoma patient set comparing patient outcome suggests that suppression of IL-1α, IL-4, IL-5, and CCL22, with concomitant elevation of CXCL10, CCL4, and CCL17, may correlate with more aggressive development of brain metastasis." (PMID 36527157, 2022). "A study of individual CSF samples from 22 patients with melanoma brain metastases and 5 disease-free controls found that Chemokine CCL22 and cytokines IL-1α, IL-4, and IL-5 were reduced in most samples, whereas a subset of molecules including CXCL10, CCL4, CCL17, and IL8 increased expression." (PMID 36527157, 2022). "Interestingly, immunokine profiling studies in the cerebrospinal fluid (CSF) of advanced melanoma patients showed that elevated levels of CXCL10, CCL17, and CCL4 may correlate with a more aggressive development of brain metastases." (PMID 33466236, 2021). "Their results demonstrated that CCL17 (but not CCL22) was sufficient to enhance melanoma cell invasiveness in the brain, and blocking CCR4 in vivo using a CCR4-antagonist small molecule reduced the tumorigenicity and micrometastasis formation of melanoma cells." (PMID 33466236, 2021). "Furthermore, levels of CCL17 mRNA correlated positively with levels of CCL22 mRNA expression (Pearson = 0.62, P = 0.06), findings that link our observations in Siah2−/− mice to clinical outcomes seen in melanoma patients." (PMID 31911617, 2020). "Chemokines CCL17 (Thymus and activation regulated chemokine (TARC)) and CCL22 (C-C motif chemokine 22) produced by tumour infiltrating macrophages may help to recruit Tregs to tumour and maintain an immunosuppressive tumour microenvironment in melanoma." (PMID 29236046, 2017). "Using a human chemokine array, we measured the secretion level of CCL17 and CCL22 from 3D cultures of microglial cells cultured with or without melanoma cells." (PMID 28415693, 2017). "Transwell migration assays using recombinant CCL17 or CCL22 revealed that CCL17, but not CCL22 (data not shown), significantly facilitated migration of the CCR4hi cells compared to control cells (CON), indicating that expression of CCR4 facilitates melanoma cell migration." (PMID 28415693, 2017).
breast cancer (27 papers, 2017 to 2024). A primary or metastatic malignant neoplasm involving the breast. "In a murine breast cancer model, the introduction of an adenoviral vector encoding CCL17 led to significant tumor regression and the generation of specific immunity in the TME, supporting a crucial role of this chemokine in the anti-tumor immune response." (PMID 37762335, 2023). "High levels of Ccl17, Cxcl13, and Cxcr3 in mammary tumors or tumor-associated macrophages induce cancer cell migration which is associated with metastasis disease." (PMID 35768767, 2022). "Among these were the chemokines Cx3cl1, Cxcl16 and Ccl17, which were considered candidate chemotactic factors for breast cancer cells with mesenchymal properties." (PMID 38055067, 2023). "A broader analysis of CXCL10 and CCL17 in CD169+ TAMs originating from various breast cancer subtypes and stages will be needed to assess their relationship in more detail." (PMID 37404831, 2023). "For instance, Wang demonstrated that C-C motif chemokine-17 (CCL-17) was secreted from CXCL14-activated fibroblasts as a regulatory factor of the CXCL14-triggered breast carcinoma cell EMT and metastasis." (PMID 34789307, 2021). "For this reason, chemokines such as CCL1/I-309 (in breast cancer), CCL17/TARC, CCL22/MDC (in gastric cancer and hepatocellular carcinoma), and CCL28/MEC (in hepatocellular carcinoma) cause Treg recruitment into the tumor niche." (PMID 33114763, 2020). "We previously reported that GM-CSF activates macrophages in vitro to express a unique set of cytokine and chemokine genes, including Mcp-1, Ccl17 and Rankl genes, whose products are demonstrated to promote the progression of breast cancer." (PMID 31888216, 2019). "The CCR4 (receptor of CCL17 and CCL22) expression level in breast cancer was reported to be associated with lung metastasis." (PMID 28039457, 2017). "Ccl17 and Cxcr3 increased in mammary tumors that protects cancer cell survival and induce tumor growth to promote breast cancer lung metastasis Hypoxia-induced chemokine Sema3a stimulates tumor-associated macrophages to the alternative type (M2), leading to pro-tumor immunity." (PMID 35768767, 2022). "We previously reported that 4T1 murine breast cancer cells produce GM-CSF that up-regulates macrophage expression of several cancer promoting genes, including Mcp-1/Ccl2, Ccl17 and Rankl, suggesting a critical role of cancer cell-derived GM-CSF in cancer progression." (PMID 31888216, 2019). "For example, we recently found that overexpression of the chemokines CXCL14 and CCL17 in mammary fibroblasts could enhance proliferation, migration, invasion of breast cancer epithelial cells, and contribute to chemo-resistance and disease relapse." (PMID 30925930, 2019). "In our previous study of transcriptome analysis of mammary tumors of PyMTSB2−/− mice, the expression levels of cancer immune modulated genes (ANXA3, CCL17, CXCL13, CXCR3, IFN-γ, NR4A1, and SEMA3a) were significantly changed." (PMID 38956496, 2024). "In breast cancer (BC), M2 macrophages produced CCL17 that induced EMT gene (N-cadherin, vimentin and PCNA) expression in tumors via CCL17/CCR4/mTORC1 axis." (PMID 38794298, 2024). "Only changes in five analytes (CXCL5, CXCL1, CCL17, CXCL10, and IL-6) were seen to overlap across all four breast cancer cell-line EV-stimulated conditions." (PMID 37441083, 2023). "After being cultured with breast cancer MDA-MB-453 cell-conditioned medium, macrophages were inclined to the M2 phenotype (IL-10 high, TGF-β high, CD163 high, CCL-17 high, CCL-22 high) in the circWWC3-transfected group as compared to the control group." (PMID 35996149, 2022). "Gene of Ccl17, Cxcl13, Cxcr3, IFN-γ, and Sema3a, were significantly decreased while the Anxa3 and Nr4a1 were significantly upregulated in SB2−/−;PyMT mammary tumors." (PMID 35768767, 2022).
breast cancer (continued). "Consistently, it has been reported that the increased expression of CCL17 and CCL22 correlates with the infiltration of CCR4-expressing Treg cells and poor clinical outcomes in gastric cancer, breast cancer, and oral tongue squamous cell carcinoma." (PMID 34885241, 2021). "Many studies have shown that CCL17 and CCL22 are highly expressed in various tumor tissues including lung cancer, colorectal cancer, gastric cancer, breast cancer, and ovarian cancer." (PMID 34885241, 2021). "Higher expression levels of CCL17 and CCL25 in breast cancer patients have been attributed to poor overall survival in the AA population, but no such correlation has been observed in the CA population." (PMID 32824813, 2020). "CCL7, CCL17, CCL20 and CCL25 are significantly more elevated in AA breast cancer patients compared to CA patients." (PMID 32824813, 2020). "As shown in breast cancer research studies, these cells in the tumor niche express CCR8 (receptor for CCL1/I-309) and CCR4 (receptor for CCL17/thymus and activation regulated chemokine (TARC) and CCL22/macrophage derived chemokine (MDC))." (PMID 33114763, 2020). "Together, CCL17 and CCL25 in AA breast cancer patients decrease overall survival, while high CCL8 decreases overall survival in CA patients." (PMID 32824813, 2020). "After the occurrence of tumour metastasis, breast cancer cells could stimulate lung tissue to secrete CCL17 and CCL22, which attract CCR4-positive Treg cells to accumulate in lung tissue, and thus facilitating lung metastasis of breast cancer." (PMID 36569832, 2022). "In MDA-MB-231 breast cancer cells, hypoxia increases CCL17/TARC expression but not in the MCF-7 line." (PMID 32781743, 2020). "CCR4, whose ligands are CCL2, CCL3, CCL5, CCL17 and CCL22, is crucial for immune cell homeostasis but is also involved in hematologic malignancies, such as adult T-cell leukemia and Hodgkin’s lymphomas, and some solid tumors, including breast cancer." (PMID 30591657, 2018). "In breast cancer, CCR4 expression positively correlates with HER2 expression, tumor recurrence, and lymph node, lung, and bone metastasis, as it enhances chemotaxis to CCL17." (PMID 30591657, 2018). "These previous results led us to hypothesize that GM-CSF produced by breast cancer cells may contribute to the establishment of tumor microenvironments by inducing the production of cancer-promoting cytokines/chemokines, such as MCP-1, CCL17 and RANKL, by tumor-infiltrating macrophages." (PMID 31888216, 2019). "The screening results showed that none of the receptors for Cx3cl1 (CX3CR1), Cxcl16 (CXCR6), Ccl17 (CCR4, DARC, CCR10) or IL6 (IL6R) was more expressed in basal B compared to basal A or luminal breast cancer cells." (PMID 38055067, 2023).
pulmonary fibrosis (27 papers, 2009 to 2025). Chronic progressive interstitial lung disorder characterized by the replacement of the lung tissue by connective tissue, leading to progressive dyspnea, respiratory failure, or right heart failure. "Moreover, CCL17 has been confirmed as a circulating biomarker of fibrosis-associated diseases, such as idiopathic pulmonary fibrosis, cystic fibrosis, peritoneal, and renal fibrosis." (PMID 35687056, 2022). "For instance, it has been reported that CCL17 drives fibroblast activation by enhancing tumor growth factor beta (TGF-β)/Smad signaling, and that anti-CCL17 antibodies attenuate fibrosis in a bleomycin-induced pulmonary fibrosis mouse model." (PMID 40269953, 2025). "Considering that CCL17 can induce lung fibrosis, stratifying patients by serum CCL17 levels and developing personalized treatments targeting CCL17 for those with high levels would be a worthwhile challenge." (PMID 40269953, 2025). "To evaluate the longitudinal expression of CCL17 in lung and serum during the development of fibrosis, we utilized a mouse model of bleomycin-induced pulmonary fibrosis." (PMID 40269953, 2025). "On the other hand, increasing evidence suggests that a Th2-mediated process including CCL17 plays an important role in the development of pulmonary fibrosis." (PMID 40269953, 2025). "CCL17 drives fibroblast activation in pulmonary fibrosis progression, enhancing TGF-β/Smad signaling." (PMID 39768150, 2024). "Monocytes preferentially differentiate into M2 macrophages under type II helper T cells (Th2) inflammation, and Th2 chemokines such as CCL17 have been shown to contribute to the development of pulmonary fibrosis in the bleomycin mouse model." (PMID 37075981, 2023). "Smoking related airway inflammation has been associated with elevated levels of CCL17 and increased concentrations of this chemokine have been found in BAL of IPF patients, suggesting its involvement in the pathophysiology of pulmonary fibrosis." (PMID 38111019, 2023). "The involvement of CCL17 in modulating the progression of diseases such as idiopathic pulmonary fibrosis has been reported, but its role in the pathogenesis of CKD remains to be elucidated." (PMID 34943853, 2021). "Humans and mice with pulmonary fibrosis were reported to have significantly elevated CCL17 and CCR4 expression in lung tissues, and the severity of pulmonary fibrosis decreased after neutralization of CCL17." (PMID 34943853, 2021). "Combined with elevated SASP mRNA expression (including Ccl2, Cxcl10, Ccl17, Mmp2, Mmp9, and Mmp12) in sorted macrophages after irradiation, we confirmed that senescent macrophages were partly contributed to lung fibrosis." (PMID 34023858, 2021). "Although lots of cytokines were regulated independently of HBoV status, several cytokines associated with lung fibrosis and tumour development, e.g., EGF, VEGF, TARC (CCL17), TNF-α, TNF-β, TIMP-1, were clearly upregulated in the HBoV-positive cohort." (PMID 26807786, 2016). "Interestingly, Arg1, C3, and Ccl17 are all genes considered to be biomarkers of alternatively activated macrophages, a cell type that requires Th2-regulated cytokines for its differentiation, and that also have been implicated in the progression of pulmonary fibrosis." (PMID 27169501, 2016). "We have previously demonstrated the selective upregulation of CCL22 and CCL17 in a rat model of radiation pneumonitis/pulmonary fibrosis." (PMID 19715610, 2009). "C–C motif chemokine ligand (CCL)-17 promotes pulmonary fibrosis." (PMID 40017805, 2025). "Moreover, underlying in vivo experimental models of pulmonary fibrosis demonstrated the key role of CCR4 ligands (primarily CCL17, but also CCL22) in tissue fibrosis, where blockade of CCL17 effects in mice resulted in lesion reduction." (PMID 38179278, 2023). "CCL17 plays an important role in the pathogenesis of pulmonary fibrosis and CXCL9 may have an antifibrotic effect in chronic bird-related HP." (PMID 31369605, 2019).